BCL2 (BCL2 apoptosis regulator)
Diseases named in the same sentence as BCL2 in open-access papers (continued):
Sharing a sentence is not in itself a finding about the gene and the disease.
pancreatic cancer (continued). "The expression of BCL-2 in pancreatic cancers is widely variable, with prevalence ranging from 0% to 55%." (PMID 11953819, 2002). "In addition, the expression of Bcl2 and Bax also indicated that CaCO3@CM-OA treatment significantly activated apoptosis signals in pancreatic cancer cells." (PMID 41377584, 2025). "Furthermore, it reduces the protein expression of Bcl-2 and increases that of Bax, triggering apoptosis in cervical cancer (Ca Ski and Hela) and pancreatic cancer (BxPC-3) cells." (PMID 40490812, 2025). "In pancreatic cancer cells (MIA PaCa-2 and PANC-1), slibinin induces apoptosis and suppresses migration by downregulating certain onco-miRNAs (miR-155, miR-222, and miR-21) and their associated targets (Bcl-2, CD34, AKT3, MASPINE, EGF, and BMP7)." (PMID 40490812, 2025). "One example would be Navitoclax (ABT‐263), which exerts its senolytic activity by targeting Bcl‐2 anti‐apoptotic proteins, and when administered in combination with gemcitabine, it was demonstrated to kill gemcitabine‐resistant and senescent‐like pancreatic cancer cells." (PMID 40717225, 2025). "Venetoclax, a selective Bcl-2 inhibitor, effectively counteracts this by downregulating gemcitabine-induced Bcl-2 overexpression, thereby promoting apoptosis and significantly increasing the sensitivity of pancreatic cancer cells to gemcitabine." (PMID 40841912, 2025). "In addition, in human pancreatic cancer cells, α‐caryophyllene reduced Bcl‐2 and increased Bax and caspase‐3 levels, exerting an apoptosis‐inducing effect." (PMID 40895140, 2025). "Moreover, exogenous HMGB1 can activate p-GSK 3β through the Wnt signaling pathway, upregulate the expression of Bcl-2 and Ki67, and downregulate the expression of E-CA in pancreatic cancer cells, thus fostering the proliferation of pancreatic cancer cells." (PMID 37897664, 2024). "Consequently, the inhibition of Bcl-2 is another pathway through which TET activates autophagy in pancreatic cancer." (PMID 38987818, 2024). "Based on these data, it can be concluded that celastrol treatment decreased the global RNA m6A modification, especially reduced the mRNA m6A modification of Claspin and Bcl-2 probably by downregulating METTL3, leading to the downregulation of Claspin and Bcl-2 in pancreatic cancer cells." (PMID 38110764, 2023). "Indeed, ABT-263, a senolytic compound targeting Bcl-2 anti-apoptotic proteins, killed gemcitabine-resistant and senescent-like pancreatic cancer cells in vitro and reduced pancreatic tumor volume when administered in combination with gemcitabine in mice." (PMID 36739330, 2023). "Additionally, Egr-1 has been found to influence the expression of BAX and BCL2 in pancreatic cancer cells, with an increase in BAX and a decrease in BCL2 observed in multiple experimental conditions." (PMID 37046823, 2023). "Moreover, our results indicated that celastrol treatment downregulated METTL3 and decreased m6A levels of Claspin and Bcl-2 mRNA, leading to the degradation of Claspin and Bcl-2 mRNA in pancreatic cancer cells." (PMID 38110764, 2023). "Additionally, it enhances apoptosis in pancreatic cancer cells by modulating the expression of apoptosis-related proteins such as Bcl-2 and Bax." (PMID 38139352, 2023). "It was proved that the combination of metformin and aspirin significantly inhibited tumor growth and downregulated the protein expression of Mcl-1 and Bcl-2 in tumors in the xenotransplantation mouse model, which has preventive significance for the occurrence of pancreatic cancer." (PMID 36829129, 2023). "Under CK21 treatment, BCL2 expression in pancreatic cancer cells was significantly reduced." (PMID 37877568, 2023). "ANGPTL8 attenuated the apoptosis of pancreatic cancer cell by down-regulating Bcl-2." (PMID 37294581, 2023).
pancreatic cancer (continued). "The results of flow cytometry and Western blot showed that wogonin may enhance the sensitivity of pancreatic cancer cells to gemcitabine by inhibiting p-Akt, anti-apoptotic gene Bcl-2, activating pro-apoptotic gene BAD, and promoting apoptosis of Panc-1." (PMID 36618921, 2022). "To assess it and to further clarify the molecular mechanisms possibly involved, we pointed our attention on MCL-1: the anti-apoptotic member of the B-cell lymphoma 2 family (BCL-2), whose protein levels correlate with malignancy, and drug resistance in many tumors, including pancreatic cancers." (PMID 35884957, 2022). "Riluzole inhibited Bcl-2 and induced Bax expression in pancreatic cancer cells." (PMID 35773307, 2022). "In support of this view, it was reported that baicalin treatment also up-regulated the mitochondrial Bax and cleaved caspase-3, while the expression of Bcl-2 protein levels was markedly decreased in a dose-dependent manner thus ultimately promoting apoptosis of pancreatic cancer SW1990 cell line." (PMID 36232344, 2022). "Targeting of BCL2 by miR-148a-3p has also been reported in colorectal and pancreatic cancers." (PMID 35022525, 2022). "We found that inactivation of the proapoptotic protein BAX alters its mitochondrial/cytosolic distribution and transcriptionally increases expression of the prosurvival protein BCL-2, which translocates into the mitochondrial outer membrane in pancreatic cancer cells." (PMID 33531986, 2021). "However, in pancreatic cancer cells, BCL-2 is expressed at normal or even decreased levels compared to normal pancreatic cells." (PMID 33669111, 2021). "The decrease of the Bcl-2/Bax ratio promotes the apoptosis of pancreatic cancer cells." (PMID 35222011, 2021). "However, for theunderstanding of the apoptotic effect in pancreatic cancer cell lines clarificationis needed on the regulation of the pro-apoptotic gene Bax and theanti-apoptotic gene Bcl2, which play a significant role in theintrinsic pathway of apoptosis." (PMID 32745158, 2020). "Also, itsanti-pancreatic cancer effect was shown by its induction of apoptosis anddown-regulation of Bcl-2 as an anti-apoptotic protein." (PMID 32745158, 2020). "Similarly, luteolin treatment resulted in a significant reduction in SW1990 tumor xenograft growth, indicating its potential in targeting Bcl-2 overexpressing pancreatic cancer." (PMID 32717779, 2020). "Apoptosis was induced by adjunctive use of rhein with epidermal growth factor receptor (EGFR) inhibitors in pancreatic cancer cells as verified by cell apoptosis analysis and changes in the expression level of apoptotic/anti-apoptotic proteins BCL-2, BAX, Caspase 3 and Cl-PARP." (PMID 30674340, 2019). "Bcl2 is expressed in the pancreatic cancer cell line PaTu 8988t." (PMID 30686270, 2019). "Moreover, defects in apoptotic pathways and the deregulation of apoptotic proteins, such as Bcl-2, Bcl-xL and Mcl-1, play decisive roles in the development and therapy resistance of pancreatic cancer." (PMID 31269745, 2019). "Inhibition of the anti‐apoptotic Bcl‐2 members by the early generation BH3 mimetics, BH3I‐2′ and HA14‐1, was associated with global and sustained Ca2+ responses induced in normal mouse PACs and in the rat pancreatic cancer cell line AR42J." (PMID 30266036, 2019). "Gossypol also inhibits Bcl-2 and Mcl-1 gene expression in pancreatic cancer cells." (PMID 29993017, 2018). "Moreover, we also found that inhibition of thestimulation of OX1R can regulate the expression levels of Bcl-2, caspase-9, and c-myc in pancreatic cancer cells." (PMID 30429828, 2018).
pancreatic cancer (continued). "Therefore, we expected that the stimulation of OX1R can promote cell proliferation through regulating Bcl-2/caspase-9/c-myc-mediated apoptosis in pancreatic cancer." (PMID 30429828, 2018). "To further investigate the possible mechanism of orexin-A-inhibited apoptosis in pancreatic cancer cells, we next examined the expression of Bcl-2, caspase-9, and c-myc proteins, which are key factors in cell apoptosis, in orexin-A-incubated PANC1 cells with or without SB408124 treatment." (PMID 30429828, 2018). "Therefore, our results indicated that orexin-A-mediated cell apoptosis occurs through regulating Bcl-2, caspase-9, and c-myc expression in pancreatic cancer cells." (PMID 30429828, 2018). "Previous studies have suggested that overexpression of CacyBP/SIP might inhibit drug-induced apoptosis by enhancing the Bcl-2/Bax ratio in pancreatic cancer cells (Xiong Chen, Apoptosis 2013)." (PMID 30234028, 2018). "Interestingly, Bcl-2, an anti–apoptotic marker, was decreased in gedunin–treated pancreatic cancer cells." (PMID 26988754, 2017). "Thus, it seems that the role of BCL2 in pancreatic cancer progression is still unclear, and further research is needed." (PMID 27689078, 2016). "Among the drugs tested, the BCL2/BCLxL inhibitor ABT-263 was identified as the one agent that synergized with Abraxane® to enhance acute induction of localized apoptosis in this model of human pancreatic cancer." (PMID 27359113, 2016). "On the other hand BCL-2 expression was undetectable in all pancreatic cancer biopsies." (PMID 26176887, 2015). "Furthermore, it has been reported that treatment with beta-adrenergic antagonists significantly suppresses the expression of p-ERK, Akt, Bcl-2, and cyclin D1, and induces the activation of caspase-3, caspase-9, and Bax in cultured pancreatic cancer cells." (PMID 25742648, 2015). "Targeting the ERK1/2-Bax/Bcl-2 pathway may in part lead to sensitization of pancreatic cancer to gemcitabine." (PMID 25880226, 2015). "This includes Bcl-2 in PANC1 pancreatic cancer cells stimulated with an agonist for TLR7 and TLR8." (PMID 26134824, 2015). "In this study, the ratio of Bax/Bcl2 was significantly increased in both pancreatic cancer cells as well as in pancreatic tumors in response to treatment with purified crocetinic acid, which suggests that crocetinic acid modulates mitochondrial function to mediate cell death." (PMID 26317547, 2015). "Similarly, EphB2 inhibition also reduced the apoptosis of CFPAC-1 cells by increasing Bcl-2 expression, with EphB2 acting as a tumor suppressor in the cell proliferation and apoptosis in pancreatic cancer." (PMID 24959213, 2014). "This anticancer effect of tumor-derived exosomes on tumor cells was already reported for other tumors, but not for CRC: exosomes secreted by human pancreatic tumor cells increased Bax and decreased Bcl-2 expression, inducing the mitochondrial apoptotic pathway in pancreatic cancer cells." (PMID 25594007, 2014). "Our findings that spiclomazine down-regulated the expression of Bcl-2 suggest that spiclomazine might induce both pancreatic carcinoma cells apoptosis." (PMID 23840452, 2013). "Western blot analysis showed that treatment of pancreatic cancer cells for 48 h with increasing concentrations of pristimerin resulted in a dose-dependent decrease in the levels of the anti-apoptotic proteins Bcl-XL and Bcl-2." (PMID 22952775, 2012).
pancreatic cancer (continued). "Since Bcl-2 Family proteins play important roles in apoptosis by functioning as promoters (e.g., Bax) or inhibitors (e.g., Bcl-2 or Bcl-xL ) of cell death process, we next studied the changes in the levels of of Bax, Bcl-2 and Bcl-xL in pancreatic cancer cells." (PMID 22952775, 2012). "Moreover, overexpression of Bcl-2 increased Hes1 expression, while siRNA to Bcl-2 reduced Hes1 expression in the pancreatic cancer cells studied." (PMID 22319533, 2012). "Oxymatrine can induce apoptotic cell death of human pancreatic cancer, which might be attributed to the regulation of Bcl-2 and IAP families, release of mitochondrial cytochrome c and activation of caspase-3." (PMID 21714853, 2011). "Furthermore, honokiol treatment led to augmentation of Bax/Bcl-2 and Bax/Bcl-xL ratios to favor apoptosis in pancreatic cancer cells." (PMID 21720559, 2011). "In pancreatic cancer, Bak (Bcl-2 antagonist/killer protein) expression and apoptosis occur in regions of chronic inflammation surrounding the cancer cells but not in the tumor cells themselves, which may simplify accelerated growth and spread." (PMID 24212603, 2010). "Our results also indicate that the CXCL12-induced gemcitabine resistance in pancreatic cancer cells might, in part, also be due to the activation of NF-κB and induction of downstream survival proteins (Bcl-2, Bcl-xL, survivin, and so on)." (PMID 21045835, 2010). "Moreover, upregulation of IGFBP6 and Bcl-2 following the reactivation of Shh-Gli1 pathway in pancreatic cancer tissues suggest regulation model of Shh-Gli1 pathway to IGFBP6 and Bcl-2 is similar in vivo." (PMID 19736394, 2009). "More importantly, our results demonstrate for the first time that the CD44+/CD133+ tumor-initiating cells, or pancreatic cancer stem cells, have a low level of miR-34 accompanied by a high level of Bcl-2, suggesting a potential link of miR-34 and its target Bcl-2 to pancreatic cancer stem cells." (PMID 19714243, 2009). "Finally PCNA, IGFBP6 and Bcl-2 mRNA were upregulated as well as Shh or Gli1 in pancreatic cancer tissues (p < 0.01)." (PMID 19736394, 2009). "Next, we examined whether miR-34 restoration could sensitize the pancreatic cancer cells with a high level of endogenous Bcl-2 expression to chemo- and radiotherapy." (PMID 19714243, 2009). "Similarly, Bcl-2 overexpression has been associated with acquired resistance of pancreatic carcinoma corresponding to our data which show upregulation X-IAP and to a somehow weaker extent of Bcl-2 in response to DEX." (PMID 16539710, 2006). "Moreover, at least one study has demonstrated that inhibition of ERK signalling in pancreatic cancer cell lines leads to downregulation of Bcl-2 and other antiapoptotic proteins, including MCL-1." (PMID 15956974, 2005). "Furthermore, protein immunoblotting experiments indicated that TET could suppress the expression of Bcl-2 in pancreatic cancer cells." (PMID 38987818, 2024). "Additionally, we noted that celastrol treatment facilitated the mRNA decay of Claspin and Bcl-2, suggesting that celastrol-mediated decrease of the m6A modification might trigger the mRNA degradation of Claspin and Bcl-2 in pancreatic cancer cells." (PMID 38110764, 2023).
pancreatic cancer (continued). "Although sustained Ca2+ responses were noted as adverse events in normal pancreatic acinar cells treated with early-generation BCL-2 inhibitors, the safety of venetoclax was confirmed in pancreatic cancer treatment, as it could maintain intracellular calcium homeostasis in normal cells." (PMID 37894324, 2023). "Additionally, Bcl-2 is normally a pro-survival protein, and a slight downregulation of Bcl-2 under combination conditions likely indicates that Bcl-2 family proteins play a role in the apoptosis of the pancreatic tumor cells." (PMID 37999116, 2023). "Moreover, we uncovered that overexpression of METTL3 partially reversed celastrol-induced downregulation of Claspin and Bcl-2, which provided the causative link between RNA m6A modification and the expression of Claspin and Bcl-2 induced by celastrol treatment in pancreatic cancer cells." (PMID 38110764, 2023). "In addition, rutin was found to promote the apoptosis of pancreatic cancer cells by upregulating the expression of apoptotic proteins, i.e., Bax, cleaved caspase 3/8/9, and by downregulating the expression of the anti-apoptotic protein Bcl-2." (PMID 35408691, 2022). "Lastly, Xu and co-workers proved that 4 could be used to treat pancreatic cancer since it increased the expression of proapoptotic protein (Bax) and decreased antiapoptotic Bcl2 protein as well as cyclin D1, whose overexpression is often related to chemoresistance." (PMID 35209235, 2022). "miR-877-3p targeted the Bcl-2 mRNA to suppress the expression of Bcl-2 to promote cell apoptosis, and our study also found that miR-877-3p could inhibit the proliferation and migration of pancreatic cancer cells." (PMID 35408691, 2022). "Notably, 8-Chrysoeriol as a natural dietary product potentially targeting BCL-2 could serve as a lead compound for SW1990 pancreatic cancer therapy." (PMID 34836055, 2021). "Therefore, we expected that regulation of GnRH might be involved in cell proliferation through induction of Bcl-2/Bax-mediated autophagy-related apoptosis in pancreatic cancer cells." (PMID 31263453, 2019). "Additionally, orexin-A treatment can protect PANC1 cells from apoptosis, whereas inhibition of the stimulation of OX1R results in apoptosis through regulating pancreatic cancer cell expression levels of Bcl-2, caspase-9, and c-myc, which are key apoptotic factors." (PMID 30429828, 2018). "Therefore, this evidence suggested that orexin-A treatment may activate theAkt/mTOR pathway to inhibit apoptosis through regulating Bcl-2/caspase-9/c-myc expression and promote cell proliferation in pancreatic cancer cells." (PMID 30429828, 2018). "This newly identified EDIL3/Bcl-2 axis might provide a further insight into the pathogenesis of pancreatic cancer and indicate a novel approaches that can be used for the treatment of pancreatic cancer." (PMID 26735172, 2016). "Study of pancreatic cancer in nude mice has shown that curcumin can suppress pancreatic cancer cell proliferation and angiogenesis by inhibiting NF-ĸB-regulated gene products such as cyclin D1, cmyc, Bcl-2, Bcl-xL, and apoptosis protein-1, COX-2, MMP, and vascular endothelial growth factor (VEGF)." (PMID 27618095, 2016). "Our study reveals that Gli1 maintained cell survival by binding the promoter regions and facilitating transcription of IGFBP6 and Bcl-2 genes in a parallel manner in pancreatic cancer cells and suggests it may be one of the mechanisms of Shh-Gli1 signaling pathway in pancreatic cancer." (PMID 19736394, 2009).